TLN1 (talin 1)
Diseases named in the same sentence as TLN1 in open-access papers (continued):
Sharing a sentence is not in itself a finding about the gene and the disease.
cancer (continued). "Talin-1 is a cytoskeletal protein that plays an important role in tumourgenesis, migration and metastasis in several malignant tumors." (PMID 25925041, 2015). "Next, an attachment assay and transwell assay clearly demonstrated that talin 1 overexpression restored, to a certain extent, the abrogated attachment and motility of cancer cells induced by miR-124 mimics." (PMID 25969668, 2015). "Interestingly, knocking down talin 1 or treatment with cyanidin-3-glucoside, a talin–integrin- interaction-targeting natural compound, inhibited the growth of HT-29 cancer micro-tumors, though the mechanism of this process is not well described." (PMID 40076426, 2025). "TLN1, locating in focal adhesion, can regulate integrin signaling and promote cancer metastasis." (PMID 38217548, 2024). "We next addressed whether TLN1 exon 17b splicing, in addition to primary cells, can also be detected in cancer cell lines." (PMID 36880935, 2023). "We next asked whether TLN1 alternative splicing is correlated with other splicing events dysregulated in cancer." (PMID 36880935, 2023). "Notably, the enriched dependency pathways reflect the same pathways that are targeted by the drugs which we associated with 17b status, thus further supporting the notion that TLN1 alternative splicing links to changes in cancer cell behavior." (PMID 36880935, 2023). "Talin1 (TLN1) plays a key role in cancer cell proliferation, adhesion, and migration." (PMID 37241967, 2023). "Moreover, the presence of TLN1 exon 17b correlates with altered drug responses and changes in gene dependencies in cancer cell lines suggesting a role in cancer physiology." (PMID 36880935, 2023). "The enrichment of TLN1 exon 17b in several cancer subtypes together with the role of TGF-β signaling in its regulation thus could have far-reaching implications in the field of cancer biology." (PMID 36880935, 2023). "Next, the analysis of cancer pathway activity showed that TLN1 may participate in the activation of EMT, PI3K/AKT, RAS/MAPK and RTK pathways." (PMID 36175877, 2022). "This suggests that, in cancer patients, elevated TLN1 levels indicate the presence of the disease and may correlate with the response to treatment or the severity of the prognosis." (PMID 34684727, 2021). "miR-429 and TLN1 have been shown to affect the biological behaviours of many carcinomas." (PMID 31068760, 2019). "Although the main biological behaviors and network of Talin-1 in cancer progression were analyzed in this study, other biological behaviors may be also important for HCC progression and deserve further attention." (PMID 28099903, 2017). "Therefore, we think that the expression of Talin-1 has tissue-specificity and further studies are needed to explore the role of Talin-1 in different cancers." (PMID 25925041, 2015). "The mechanism of action of Talin-1 during the development and progression of cancer is poorly characterized and may be complex." (PMID 25925041, 2015). "Alternatively, TLN1 in GBM may contribute to invasion of cancer cells via survival signaling pathways by activating ECM-integrin–mediated signaling and promoting anoikis resistance." (PMID 26336988, 2015). "Talin-1 is a cytoskeletal protein that acts as a key adaptor protein to regulate integrin conformation and cell migration, and has been shown to play an important role in promoting tumor cell adhesion, migration and invasion in different types of cancer." (PMID 25925041, 2015). "Additionally, cancer disease pathways showed 37 proteins at high levels, including integrin beta-3, integrin alpha-IIb, vinculin, actin, cytoplasmic 1, Ras-related protein Rap-1b, and talin-1." (PMID 40564899, 2025). "Therefore, talin-1 may serve as a molecular marker of cancer progression and a novel prognostic biomarker in these patients." (PMID 37942198, 2023). "Therefore, talin-1 may have the potential as a novel poor prognostic biomarker of cancer-related death and progression of the disease in OC patients." (PMID 37942198, 2023).
cancer (continued). "Recent studies have suggested that RHOJ is preferentially expressed in epithelial-to-mesenchymal transition cells, with interaction with proteins (FLNB, TLN1 and IPO9) that regulate nuclear actin and inhibit actin polymerization in cancer cells." (PMID 39984455, 2025). "Most signaling pathways in pan-cancer, including ACTB, FLNA, MYH9, MYH10, and TLN1, exhibited high activation levels in the epithelial-mesenchymal transition (EMT) pathway, but consistent inhibition of the cell cycle, DNA damage response, and hormone AR." (PMID 38862242, 2024). "Downregulation of TLN1, ITGB3, and TUBA4A with simultaneous upregulation of HSPG2 protein were observed in cancer samples compared to healthy controls." (PMID 37241967, 2023). "Therefore, disruption of TLN1 might be a potential strategy for cancer therapy." (PMID 35285795, 2022). "According to the database annotation, universal EV proteins (CDC42, GNAI2, ITGB3, TLN1, and TUBA4A) are involved in platelet activation that help cancer cells escape immune surveillance and provide a prometastatic microenvironment." (PMID 32916986, 2020). "Odds ratios were calculated, and the biomarkers that showed significant difference between Non-cancer and CaP were free/total PSA (p = 0.003), TARDBP (p<0.001), TLN1 (p = 0.006) and CALD1 (p<0.001)." (PMID 31404106, 2019). "Most cancer types showed a negative correlation between disulfidptosis-related genes and methylation, expected for TLN1 and MYL6." (PMID 38584831, 2024). "Analysis of differential junction expression in TCGA data across all cancers identified such a non-annotated splice event in TLN1 mRNA." (PMID 36880935, 2023). "To date, the mechanisms that lead to the high and low expression levels of talin-1 in various cancers are not very clear." (PMID 37942198, 2023). "In the past decades, a large number of studies have demonstrated the biological function of TLN1 in the development of several types of cancers, including GC, but there is little evidence with regard to the role of TLN2 in GC metastasis." (PMID 32256587, 2020). "To date, the mechanisms leading to the high expression of Talin-1 in human cancers are not very clear." (PMID 25925041, 2015). "To demonstrate that this role is not cell specific but rather independent of the carcinoma cell type, we also induced knockdown of talin-1 in A431 and SCC-9 LN1 cell lines and observed a decrease in cell adhesion, migration and invasion." (PMID 24858105, 2014). "However, through differential pre-mRNA splicing analysis, we discovered a cancer-enriched, non-annotated 51-nucleotide exon in TLN1 between exons 17 and 18, which we refer to as exon 17b." (PMID 36880935, 2023).
tumor (61 papers, 2014 to 2026). "The talin-1 protein was overexpressed in OSC tissues, and a high expression level of talin-1 was found to be significantly associated with tumor aggressiveness and poorer DSS or PFS." (PMID 37942198, 2023). "Poor histological grading in cutaneous SCC is associated with tumor recurrence, metastasis, and invasive phenotype of the tumor, and it was associated with Talin-1 upregulation in our study." (PMID 37013489, 2023). "TLN1 loss inhibited the expression of stem cell-associated proteins and mesenchymal proteins, and impeded invasion and in vivo tumor growth." (PMID 26336988, 2015). "Also, talin-1 protein expression was associated with more aggressive tumor behavior, more advanced disease, and poor DSS, especially in patients in the advanced stage of the disease (stage III) or in OSC patients with poor PFS." (PMID 37942198, 2023). "Their findings revealed that silencing Talin 1 significantly impaired tumor cell adhesion to the vasculature, while FAK inhibition had an even greater impact, notably reducing the tumor cells’ capacity for TEM." (PMID 41123820, 2025). "Other studies focus on elucidating how TLN1 promotes tumor cell invasiveness, proliferation, and metastasis." (PMID 39951434, 2025). "In this study, highly abundant Ezrin (EZR), Talin-1 (TLN1), Adenylyl cyclase-associated protein 1 (CAP1), and Moesin (MSN) have been used as exosomal tumor biomarkers." (PMID 39001524, 2024). "CircRNA_400029 promotes the malignant biological behavior of CC by regulating the miR-1285-3p/TLN1 axis and inhibiting apoptosis, and downregulation of CircRNA_400029 can suppress tumor growth in nude mice." (PMID 38309290, 2024). "Since talin-1 plays an important role in the interaction between integrin, cytoskeleton, and ECM, dysregulation of this protein has been linked to tumor metastasis and invasion." (PMID 37942198, 2023). "It is noteworthy that the level of expression of talin-1 was significantly higher in the OSC tissues compared to the benign tumors and normal tissue samples." (PMID 37942198, 2023). "Talin-1 as a component of multi-protein adhesion complexes plays a role in tumor formation and migration in various malignancies." (PMID 37013489, 2023). "Immunohistochemistry of TLN1 showed that TLN1 was ubiquitously expressed in the membrane and cytoplasm of paraneoplastic and tumour tissues." (PMID 35285795, 2022). "Silencing TLN1 in TNBC cells significantly attenuated the migration of tumour cells through interfering the dynamic formation of focal adhesion with integrin β1, thus regulating FAK-AKT signal pathway and epithelial-mesenchymal transformation." (PMID 35285795, 2022). "Since TLN1 is crucial for tumour cell adhesion and metastasis, we tested the effect of silencing TLN1 on MDA-MB-231 cell adhesion, migration, and invasion in vitro." (PMID 35285795, 2022). "Western blotting of freshly dissected TNBC tumours revealed that the relative protein levels of TLN1 in TNBC tumour tissues were significantly higher than those in para-cancerous breast tissues." (PMID 35285795, 2022). "The underlying mechanism is circRNA_400029 as a competitive endogenous RNA, through circRNA_400029/ miR-1285-3p/ TLN1 axis regulates the expression of TLN1, further affecting tumor growth, invasion and metastasis and changing cell cycle." (PMID 35069901, 2022). "More importantly, silencing TLN1 was shown significant reduction of tumour size and weight in NOD/SCID mice implanted with 106 MDA-MB-231/NC or shTLN1 cells in the mammary fat pad." (PMID 35285795, 2022). "Taken together with the results reported previously, our observations suggested that miR-429 functions as a tumour suppressor via downregulation of TLN1 in NPC." (PMID 31068760, 2019). "Targeting TLN1 was shown to reduce invadopodium formation, tumor invasion, and metastasis in case of MDA-MB-231 cells." (PMID 31269666, 2019). "The slower tumor growth and lower tumor weight in the treatment group correlates with reduced TLN1 expression." (PMID 31269666, 2019).
tumor (continued). "These corroborate previous reports that TLN-1 is involved in integrin activation, which leads to the regulation of adhesion, invasion, proliferation, anoikis, survival, tumor progression and metastasis." (PMID 26822056, 2016). "In line with this, reciprocal communication between extracellular matrix and tumor cells is recognized as a major tumor microenvironment and TLN1 are known to be a key regulator in this process." (PMID 26336988, 2015). "Tumor cells with either NT shRNA or TLN1 shRNA were transplanted for orthotopic tumors, and tumor-bearing mice were treated with Bevacizumab." (PMID 26336988, 2015). "Among the identified proteins, we first validated by immunoblotting the higher expression of talin-1 in tumor tissues compared with control tissues obtained from the orthotopic murine model (Student's t-test, p<0.05)." (PMID 24858105, 2014). "Of note, certain proteins exhibited site-selective variation in phosphorylation between different tumour types, examples being Tln1 and Cbl." (PMID 25200860, 2014). "In vivo studies further confirmed that silencing circRNA_400029 or TLN1 suppressed tumor growth." (PMID 41148856, 2025). "Interestingly, Talin-1 expression was increased in MCs surrounding tumor lesions in the peritoneum of EOC patients." (PMID 38254102, 2024). "The dysregulation of talin-1 expression existed in tumor tissues from OSC patients." (PMID 37942198, 2023). "Additionally, the results of the UALCAN database demonstrated that the expression of talin-1 was significantly reduced in the primary tumor of OC compared to the normal tissue samples (P<0.0001)." (PMID 37942198, 2023). "Our findings indicated that there is a statistically significant association between high expression levels of Talin-1 and advanced TNM stage (Hscore P = 0.024), LVI (intensity of staining P = 0.024; H-score P = 0.023) as well as tumor recurrence (Hscore P = 0.006)." (PMID 37013489, 2023). "In addition, the Talin-1 was indicated to play a pivotal role in enhancing the cell adhesion, cell proliferation, and angiogenesis in previous tumor relevant reports." (PMID 31215474, 2019). "TLN1 is a cytoskeletal protein, which was shown to be a tumour promoter in NPC." (PMID 31068760, 2019). "Recent studies have revealed that Talin-1 plays a substantial role in the metastasis process of tumor cells, influencing cell proliferation by recruiting and activating focal adhesion proteins, as well as influencing an association of integrin adhesions with cell cycle progression." (PMID 31215474, 2019). "Some studies have demonstrated that talin 1 is closely related to tumor metastasis." (PMID 25969668, 2015). "Notably, mice with TLN1 K/D tumor and Bevacizumab survived more than 3 months (median survival days; Bev, 51 days; shTLN1+Bev, 92 days, p < 0.001)." (PMID 26336988, 2015). "Furthermore, TLN1 K/D significantly delayed growth of highly aggressive AR tumor (median survival, NT shRNA-AR, 21 days and shTLN1-AR, 28 days, p < 0.001)." (PMID 26336988, 2015). "Although exact pathway to which TLN1 is driving stem-like invasive tumor phenotypes and Bevacizumab-resistance is yet to be determined, potent effects of TLN1 targeting on GBM cell growth and Bevacizumab-resistance strongly supports TLN1 as a potential therapeutic target." (PMID 26336988, 2015). "We hypothesized that TLN1 targeting would potentiate Bevacizumab-mediated anti-tumor effects in patient-derived GBM tumors." (PMID 26336988, 2015). "Talin-1 demonstrated the highest fold-change in tumor tissues (Fisher's exact test, p<0.05) and its expression was validated by immunoblotting (Student's t-test, p<0.05), qRT-PCR (Student's t-test, p<0.05) and immunohistochemistry in OSCC human tissues (Students' t-test, p<0.0001)." (PMID 24858105, 2014).
tumor (continued). "In fact, we found several proteins possibly involved in actin cytoskeleton organization and cell-cell junction assembly, including talin-1, ezrin, plastin-3, fascin, catenin alpha-1, filamins A and B to be up-regulated in tumor tissues compared to control tissues." (PMID 24858105, 2014). "Interestingly, we also noted phosphorylation of proteins associated with cell adhesion and migration, such as VASP and TLN1, which may facilitate interactions with the supportive tumor microenvironment." (PMID 40129242, 2025). "However, TLN1 protein was found to be upregulated in tumor specimens." (PMID 38467852, 2024). "Additionally, mRNA levels of ACTB, DSTN, FLNA, and TLN1 increased gradually with the tumor stage." (PMID 37325625, 2023). "Moreover, HCC studies have found both up- and downregulation of talin-1 in tumor tissues." (PMID 37942198, 2023). "Previous studies have revealed several abnormally expressed genes in NPC that could serve as reliable prognostic factors, like H3K27me3, ULK1, LOX, Talin-1 and PTP4A3, however, the existing molecular markers are substantially limited in identifying tumor spread and aiding risk assessment." (PMID 29100406, 2017). "Thus, the observed changes of cell cycle distribution, anoikis, migration and invasion, and tumor formation inhibition in vivo were likely associated with the down-regulation of TLN-1 and TLN-2, not just TLN-1." (PMID 26822056, 2016). "Knockdown of TLN1 inhibited proliferation, migration, invasion, and epithelial-mesenchymal transition (EMT), promoted apoptosis in CRPC cells, and suppressed tumor growth in vivo." (PMID 42112334, 2026). "Specifically, an elevation in the expression levels of PRN1, OXSM, SLC3A2, and CD2AP were observed in tumor tissues, while the expression levels of DSTN, FLNA, TLN1, IQGAP1, MYL6, NCKAP1, and NDUFS1 declined in tumor tissues." (PMID 39995998, 2025). "Results showed that ACTB, DSTN, FLNA, IQGAP1, MYL6, and TLN1 were overexpressed in normal tissues, while CD2AP and INF2 were overexpressed in tumor tissues." (PMID 37325625, 2023). "Finally, the circRNA_400029/miR-1285-3p/TLN1 axis could affect tumor growth in vivo." (PMID 35069901, 2022). "Therefore, we postulated that miR-429 may act as tumour suppressor by targeting TLN1 in NPC." (PMID 31068760, 2019). "Intravenous delivery of CTNNA1 siRNA with CA nanoparticles significantly reduced tumor volume in the initial phase of the study, while siRNAs targeting CTNNB1, TLN1, VCL, PXN, and ACTN1 genes significantly decreased the tumor burden at all time points." (PMID 31269666, 2019). "By developing in vivo Bevacizumab- resistant tumor models and utilizing a series of patient-derived GBM models, we have identified and validated TLN1 as a key mediator of Bevacizumab-resistance in GBM." (PMID 26336988, 2015). "Using these U87-derived Bevacizumab-resistant tumor and the patient-derived primary GBM models, we identified that TLN1 was significantly upregulated by Bevacizumab treatment." (PMID 26336988, 2015). "Having shown the role of TLN1 in GBM cells in vitro, we attempted to address the role of in vivo tumor propagation and, more importantly, in vivo Bevacizumab-resistance." (PMID 26336988, 2015). "This study showed that miR-429 functions as a tumour suppressor in NPC by downregulation of TLN1, although the relationship is not direct." (PMID 31068760, 2019). "The aim of this study was to prospectively validate a gene expression panel (composed of GAPDH, VIL1, CLU, TIMP1, TLN1, LOXL3 and ZEB2) for detecting circulating tumor cells (CTCs) as prognostic and predictive tool in blood samples from 94 metastatic CRC (mCRC) patients." (PMID 28608814, 2017). "Moreover, Bivariate analysis showed a statistically significant positive correlation between increased Talin-1 expression and increase in TNM stage (Spearman’s rho, P = 0.025), and between high Talin-1 expression and LVI (P = 0.023) as well as tumor recurrence (P = 0.005)." (PMID 37013489, 2023).
tumor (continued). "Interestingly, WISP1 was also shown to promote tumor cell metastasis by activating PI3K/Akt/mTOR signaling, which indicates that Talin-1 may promote cell adhesion via the classic mTOR pathway." (PMID 28099903, 2017). "Importantly, histological analysis also revealed that TLN1 K/D tumors do not have protruding invasive cells at the margin despite Bevacizumab treatment, suggesting that TLN1 K/D negates Bevacizumab-induce invasive tumor growth pattern." (PMID 26336988, 2015).
infection (6 papers, 2016 to 2023). The state of being infected such as from the introduction of a foreign agent such as serum, vaccine, antigenic substance or organism. "In conclusion, the results from our study demonstrate that talin-1 plays a pivotal role in host response to infection by C. rodentium." (PMID 36951501, 2023). "Tln1-deficient BMmacs expressed a modest 6% increase of CD11b compared to Tln1fl/fl BMmacs with and without infection." (PMID 38102166, 2023). "Tln1 mRNA and talin-1 protein levels remained significantly reduced in whole tissues of Tln1Δepi mice with and without infection." (PMID 36951501, 2023). "While the percentage of CD11b+ cells were not different between genotypes, we found that CD11b+Tln1-deficient BMmacs expressed higher levels of CD86, but not MHCII, compared to Tln1fl/fl BMmacs with infection." (PMID 38102166, 2023).